TNF (tumor necrosis factor)
Diseases named in the same sentence as TNF in open-access papers (continued):
Sharing a sentence is not in itself a finding about the gene and the disease.
co-infection (continued). "Additionally, some reports have described that the co-infection of both bacteria promotes increases in the expressions of TNF-α, IL-1β, and IL-6 in murine in vivo models." (PMID 38612423, 2024). "We found that HIV co-infection in LTB-infected individuals caused a significantly lowered production of PPD-induced Th1 (IFN-gamma and IL-2) cytokines by PBMCs and the systemic pro-inflammatory (TNF-alpha and IL-6) cytokines in plasma." (PMID 39514524, 2024). "Thus, OKF6/TERT2 cells were infected with P. gingivalis, F. nucleatum, the co-culture of both bacteria, and the co-infection of both bacteria and then the mRNA levels of TNF-α, IL-1β, IL-6, and IL-8 were determined using RT-qPCR." (PMID 38612423, 2024). "TNF-α-secreting CD8+ T cells may be more sensitive for evaluating the early efficacy of anti-TB treatment in patients with HIV/TB co-infection." (PMID 37483385, 2023). "After co-infection, the main CD8β cytokine producers were TNF+IFN-γ+, which peaked at 28 dpi." (PMID 37287962, 2023). "TNF-α-secreting CD8+ T cells may be a more sensitive marker for early evaluation of anti-TB treatment efficacy in patients with HIV/TB co-infection." (PMID 37483385, 2023). "TNF-α-secreting CD8+ T cells might be more sensitive for evaluating the early efficacy of anti-TB treatment in patients with HIV/TB co-infection." (PMID 37483385, 2023). "Additionally, pro-inflammatory cytokines IL-1β, IL-6, CXCL2, and TNF-α are downregulated during co-infection compared to P. aeruginosa single-infection." (PMID 37305417, 2023). "All those indicate that TNF-α-secreting cells may respond to the early stage of anti-TB treatment in both HIV/TB co-infection and TB." (PMID 37483385, 2023). "When the cytokines' levels were compared between groups of patients according to therapy and protozoa infection status, we found that the levels of TNF-α were higher in patients with coinfection (p = 0.016), particularly in the group of patients under antirheumatic treatment." (PMID 35492365, 2022). "The reason might be that the expression of TNF-α in cells was down-regulated by HIV/MTB co-infection through some mechanism." (PMID 36619740, 2022). "Other factors that can negatively interfere with Te production in HIV patients include metabolic derangement as well as concomitant liver alterations with Hepatitis B Virus (HBV) or HCV co-infection, and the presence of inflammatory cytokines such as TNF-α and interleukin-1." (PMID 34440836, 2021). "Notably, some upregulations in pro-inflammatory markers IL-8, TNF receptor sTNF-rII, and TNF-α have been documented in schistosome-HIV coinfection, possibly consistent with heightened Th1 response following recent HIV acquisition." (PMID 34015063, 2021). "The top three markers contributing most to overall network density by AUC in the subgroup of those without HIV-1 co-infection were CXCL10, C-reactive protein, and IFNα2, whereas the top three markers in the subgroup of those with HIV-1 co-infection were IL-17A, IL-1β, and TNFα." (PMID 34386782, 2021). "While it is unclear whether MAIT cells have a direct role in antimycobacterial immunity, SIV co-infection clearly affects their ability to secrete certain cytokines, such as TNFα." (PMID 32433713, 2020). "Associations between the occurrence of ME/CFS clinical symptoms, HHV−6, HHV−7 and B19 infection/co-infection reactivation, and increased expression levels of TNF-α and IL6 have been observed, as well as alterations in the levels of infection markers of B19V and EBV." (PMID 32455633, 2020). "However, we found a lower frequency of MAIT cells producing TNFα after Mtb co-infection in response to both the E. coli and M. smegmatis stimuli." (PMID 32433713, 2020). "However, TNF-α responses are severely impaired during the early phase of co-infections, leading to a failure to control bacterial outgrowth and Spn infection." (PMID 30333833, 2018).
co-infection (continued). "However, the co-infection between Plasmodium vivax and enteroparasitoses increased levels of TNF-α, and IL-10 in comparison to those with single malarial infection." (PMID 29293589, 2018). "perfringens co-infection and C. perfringens infection alone with high fishmeal diet could up-regulated the IL-8 and TNF-α transcript level in chickens respectively." (PMID 30483244, 2018). "In a mouse model of vulvovaginal candidiasis (VVC), the fungal burden and the levels of pro-inflammatory cytokines, IL-1β, IL-6 and TNF-α showed a increase on co-infection with S. agalactiae, while the level of TH17 T cells and IL-17 in the cervicovaginal lavage fluid were significantly decreased." (PMID 29527193, 2018). "In contrast, TNF-α production by NK cells was reported in response to Escherichia coli infection, and in an influenza virus and Staphylococcus aureus co-infection mouse model." (PMID 28706510, 2017). "Only IFN-ω, TNF-α, IL-6 and IP-10 were in fact differentially modulated during co-infections." (PMID 28644900, 2017). "To examine the immune profile of individuals with co-infection, we compared the concentration of 15 immune markers (IL-1β, IL-6, IL-8, TNF-α, IL-7, G-CSF, MCP-1/CCL2, MIP-1-α/CCL3, IL-12, IFN-γ, IL-13, IL-17A, GM-CSF, IL-10, and TGF-β1) among the three groups using Kruskal-Wallis ANOVA." (PMID 27128316, 2016). "Similarly the greatest frequency of PD-1 expression in MTB-specific cells secreting IFN-γ and TNF-α was seen in patients with active TB /HIV co-infection (p = 0.010) with a similar trend in tri-functional cells." (PMID 26756579, 2016). "Coinfection induced severe disease and a fulminant immune response, comprised of massive recruitment of inflammatory monocytes, neutrophils and other immune cells, and strong upregulation of many proinflammatory cytokines including TNF-α, KC and MIP-2." (PMID 26265006, 2015). "Coinfection caused a large increase in TNF-α, which was largely absent in both single infections (Fig1J)." (PMID 26265006, 2015). "This study, to the best of our knowledge, represents the first report reflecting the delicate link between NF-κB, TNF-α, IL-6, FoxP3 splice variants and HO-1 genes and their relationship with HIV disease progression and explains how Mtb co-infection modulates these links to the advantage of HIV." (PMID 25198707, 2014). "Inflammatory cytokine IL-8 and tumor necrosis factor (TNF)-α levels of porcine enterocytes treated with Lawsonia intracellularis alone or in the presence of S. enterica serovar Typhimurium were elevated significantly, and synergistic effects were observed in case of co-infection." (PMID 38672139, 2024). "The IL-10/TNF-α ratio was on average 30-fold (69.9 [12.5–140.7]), 10-fold (19.7 [1.6–115.2]), 6-fold (13.0 [3.5–24.9]) and 8-fold (16.9 [2.4–86.6]) higher in those with single or P. falciparum co-infections with filariae, STH and intestinal protozoa, respectively, than in uninfected participants." (PMID 35421083, 2022). "Or the TNF-α-secreting cells may die through certain pathways in the case of HIV/MTB co-infection." (PMID 36619740, 2022). "Furthermore, inhibition of NK cell-dependent TNFα production results in decreased AM phagocytic activity and reduced S. aureus clearance, demonstrating the altered anti-bacterial activity of AMs during co-infection." (PMID 34067487, 2021). "Co-infection of E. maxima with C. perfringens suppressed the expression of IFNα, IFNγ, IL-1β, IL-2, IL-12, IL-13, IL-17, NO, and transforming growth factor-β4 genes, but increased the expression of IL-8, IL-10, IL-15, and lipopolysaccharide-induced TNFα factor." (PMID 33193291, 2020). "In addition, co-infection patients should be treated with classic sulfonamide therapy when they were accepted with etanercept and other biological anti-TNF agents, which could reduce the lesion size and inflammation." (PMID 30519229, 2018). "Interestingly, a clear synergistic effect on IL-6, CCL5 and TNF-α up-regulation could be observed after co-infection." (PMID 27213692, 2016).
co-infection (continued). "Indeed, our baseline analysis confirmed the strong association of sCD14 with age, the link of HCV co-infection with three soluble markers (IP-10, sICAM-1 and sVCAM-1), and identified a striking association of several cytokines, TRAIL and TNF-α among other, with the cART regimen (PI- or NNRTI-based)." (PMID 25462535, 2014). "Collectively, interferon-related pathways were shared across infection states, whereas suppression of TNF/NF-κB and enrichment of coagulation and metabolic pathways distinguished HIV-Mtb co-infection from HIV mono-infection." (PMID 41394852, 2025). "More recently, IFN-γ and TNF levels have been correlated with severity and death as well as clinical findings such as vomiting and dyspnea in patients with VL/HIV co-infection." (PMID 40145085, 2025). "However, it is worth noting that P. berghei ANKA co-infection resulted in a significant increase in TNF levels in mice with an ongoing L. major infection compared to mice infected with L. major alone, which may contribute to improving L. major parasite control." (PMID 40720541, 2025). "Low but detectable increases in IL-1α, IL-4, MIP-1α, MIP-1β, TNF, fractalkine and RANTES occurred upon Mtb infection and Mtb/HIV-1 co-infection, depending of the cell type." (PMID 40420159, 2025). "The baseline lipid profile, CD4+ cell count, platelets, CRP, PCT, TNF-α, VCAM-1, and HCV and HBV coinfection were evaluated." (PMID 40006998, 2025). "In contrast, co-infection upregulated the induction of IFN-β, IFN-λ2/3, IL-1β, and TNF-α expression." (PMID 40431161, 2025). "In contrast, the expression levels of IL-6, IL-8, and TNF-α were decreased in cells coinfected with vL126A/ΔNLS and S. suis compared to wild-type PRRSV-2 and S. suis co-infection." (PMID 38547254, 2024). "HIV coinfection can lead to EBV reactivation, consequently increasing plasma concentrations of IFN-γ and TNF-α." (PMID 39066175, 2024). "We hypothesized that ESAT6/CFP10 TNF and IL-2 responses improve Mtb infection detection among exposed household contacts (HHCs) and are associated with index case Mtb aerosolization (i.e., cough aerosol culture positive for Mtb growth, CAC+]) and HIV co-infection." (PMID 39606489, 2024). "Co-infection of monocytes with PRRSV-2 strain IAF-Klop and S. suis led to synergistic effects on the expressions of IL-6, CCL5, and TNF-α, and additive effects on productions of CCL4, CCL14, CCL20, IL-15, and PTGS2 (COX-2)." (PMID 38547254, 2024). "Peihu Fan’ team discovered that the HP-PRRSV/PCV2 co-infection group had up-regulated serum concentrations of TNF-α and IL-10, while IFN-γ was lower in the co-infection groups, especially the HP-PRRSV/PCV2 group, than in the single-infection groups." (PMID 36992486, 2023). "In contrast, co-infection induced exclusively H3N2-specific single-cytokine producers CD4+ T cells (85% of IL-2, 8.8% of TNF, and 4% of IFN-γ)." (PMID 37287962, 2023). "A previous study showed that co-infection of PAMs with PRRSV and Mycoplasma hyopneumoniae considerably increased the expression of pro-inflammatory cytokines TNF-α and IL-1β." (PMID 36992486, 2023). "Further, TNF-α, IL-1β, and IL-10 levels correlated with ALT suggesting a role in liver damage in the setting of co-infection." (PMID 37877022, 2023). "Namely, we observed a significant decrease in the production of IFN-γ, TNF-α, IL-1β, IL-15, and IL-17 in patients with HIV/TB coinfection compared to the group of patients with HIV-1 and TB monoinfections." (PMID 37376629, 2023). "In summary, we have shown that patients with HIV-1/TB coinfection are characterized by reduced plasma levels of five proinflammatory cytokines: IFN-γ, TNF-α, Il-1β, IL-15, and IL-17, which are crucial for the control of both infections." (PMID 37376629, 2023). "At the same time, a drastic decrease in the plasma levels of IFN-γ, TNF-α, Il-1β, IL-15, and IL-17 was detected in patients with HIV/TB coinfection compared to patients with HIV-1 or TB monoinfections." (PMID 37376629, 2023).
co-infection (continued). "The expression levels of TNF-α in all PCV2 and PRRSV co-infection groups were significantly up-regulated compared to the PCV2 alone group at 12 to 48 hpi." (PMID 36992486, 2023). "We showed that if IL-1β, TNFα and OSM were present in uninfected excisional skin lesions, IL-17A, IL-17F and IL-22 were specifically produced after S. aureus and P. aeruginosa co-infection of the lesions." (PMID 36275755, 2022). "Compared with HCs and patients with TB, a lower percentage of tumor necrosis factor α (TNF-α) secreting DP T cells and a higher percentage of granzyme A-secreting DP T cells were observed in patients with HIV mono-infection and HT coinfection, respectively." (PMID 35712309, 2022). "Coinfection increased the percentage of CD4+, CD4+IL4+ and CD8+IL4+ cells and decreased TNF-α secretion after BCG stimulation in the spleen when compared with the BCG infection alone." (PMID 33936040, 2021). "After co-infection (Ctrl + PRRSV-2/H3N2), TNF, IFN-γ, IL-12p40, IL-4 and CXCL-13 transcripts were all up-regulated (mean fold change of 2.43, 1.86, 3.47, 2.49 and 2.83, respectively)." (PMID 34858411, 2021). "In the Vac group, PRRSV-2/H3N2 co-infection induced a proportion of IFN-γ+ CD8+ T cells (mean 0.23%) and a significantly greater proportion of TNF+ CD8+ T cells (mean 0.35%) compared to Vac + PRRSV-2 (mean 0.02%; p<0.5)." (PMID 34858411, 2021). "This leads to the uncontrolled activity of T cells and an enormous secretion of cytokines such as TNFα and IFN-γ, resulting in an increase in the inflammatory potential during co-infection." (PMID 34067487, 2021). "In our study, we combine SIV with Mtb co-infection to show that that SIV can induce activation of MAIT cells in vivo, and can also impair their ability to produce TNFα upon co-infection with Mtb." (PMID 32433713, 2020). "SIV and Mtb co-infection led to increased expression of the activation/exhaustion markers PD-1 and TIGIT, and decreased ability to secrete TNFα when compared to SIV-naïve MCM." (PMID 32433713, 2020). "The levels of TNF-α, IL-1β, IL-6, IL-10, IL-12, mKC, and IFN-γ were significantly increased at 4 h or/and 24 h after MRSA co-infection." (PMID 31849655, 2019). "In summary, HBV-infected patients had a unique biomarker clustering profile comprising IFN-γ, IL12p70, IL-10, IL-6, and TNF-α that was distinct from the profile of the healthy controls and from those with HBV/HIV coinfection." (PMID 30815625, 2019). "We highlight the roles of matrix metalloproteinases, neutrophils, eicosanoids and cytokines, like tumor necrosis factor-α and interleukin 1β, as well as the role of HIV co-infection." (PMID 30425706, 2018). "Nonetheless, these results corroborate evidence for elevations in IP-10 and TNFα in HIV and for IP-10 levels in HIV+HCV co-infection." (PMID 29408932, 2018). "Various effects of in vivo co-infection of T. gondii and E. tenella in chickens were observed on IFN-γ, TNF-α, IL-10 and IL-12." (PMID 30081942, 2018). "This is in accordance with another study showing that T. muris evoked an increase in pro-inflammatory cytokines such as TNF-α along with an increase of IL-4 and IL-10 compared to BCG infection and co-infection." (PMID 28192437, 2017). "Immune modulators that increased during co-infections compared to CHIKV mono-infection were IFN-ω (2.8 fold, p<0.001), TNF-α (1.38 fold, p = 0.011) and IFN-β (5.26 fold, p = 0.003 at 24 hpi)." (PMID 28644900, 2017). "Overall we could observe a tendency for reduced levels of IFN-γ, TNF, IL-6, and IL-10 in the serum of co-infected groups, when compared to P. yoelii 17XNL single infected group, suggesting a modulation of P. yoelii 17XNL induced immune response by Leishmania co-infection." (PMID 27446022, 2016). "The level of TNF-α was significantly higher in patients infected with EBV, while TGF-β in patients with HPV infection and EBV/HPV co-infection." (PMID 27547238, 2016).
co-infection (continued). "We conclude that inflammatory monocytes recruited early, during the viral phase of coinfection, induce TRAIL-mediated lung damage, which facilitates bacterial invasion, while TNF-α and neutrophil responses help control subsequent bacterial outgrowth." (PMID 26265006, 2015). "They observed that the elevation in TNF-α and NF-κB was influenced by the age of the mice, the type of virus (i.e RSV and hMPV) and single versus co-infection." (PMID 24932493, 2014). "Co-infection with E3LΔ26C virus blocked the induction of IFN-α and TNF by CpG, myxoma virus, or Heat-VAC, indicating that the dsRBD at the C-terminus of E3 is not required for this inhibition in human pDCs." (PMID 22606294, 2012). "Elevation of TNF-α, which is secreted from HIV-1-infected macrophages or microglia, has been widely shown to occur in response to hepatitis C virus (HCV) co-infection or methamphetamine abuse in HIV-1 infection settings." (PMID 23078780, 2012). "Co-infection with E3LY48A virus inhibited the production of IFN-α and TNF by CpG, myxoma virus, or Heat-VAC in pDCs, to a similar extent as co-infection with WT vaccinia." (PMID 22606294, 2012). "Whereas co-infection with WT vaccinia significantly attenuated the induction of IFN-α and TNF by myxoma virus, Heat-VAC or CpG, co-infection with ΔE3L or E3LΔ83N virus only partially reduced IFN-α and TNF secretion." (PMID 22606294, 2012). "The co-infection with H3N2 SwIV and either SW114 or Nagasaki induced higher levels of IL-1β, TNF-α, IL-6, IL-12 and IL-10 compared to mock or H3N2 SwIV infection alone." (PMID 23157617, 2012). "In co-infection, intra-hepatic HIV-specific CD8+ and CD4+ T-cells producing IFN-γ and TNF-α were detected and were comparable in frequency to those that were HCV-specific." (PMID 18941622, 2008). "The TAK-242/siRNA-treated IAV+SA group exhibited markedly decreased mRNA levels of inflammatory factors (NF-κB, IL-6, TNF-α) and adhesion molecules (ICAM-1, VCAM-1) compared with the uninfected IAV+SA group, confirming TLR4 as the key receptor mediating co-infection-induced inflammation." (PMID 40572089, 2025). "Understanding the levels and interactions of IFN‐γ and TNF in the setting of HIV and SARS‐CoV‐2 co‐infection could provide valuable insights into the mechanisms driving disease progression and immune dysfunction." (PMID 40135792, 2025). "Indeed, similar to T-cell activation, the plasma levels of pro-inflammatory cytokines (IFN-γ, IL-6, IL-8, TNF, and MIP-1β) were higher in patients with VL/HIV co-infection than in those with HIV or VL mono-infection and healthy individuals." (PMID 40145085, 2025). "We assessed the utility of Mtb-specific TNF and IL-2 (from supernatants of the QFT Plus TB1 antigen tube) in improving Mtb infection detection in HHCs of TB participants and the effect of index case aerosolized Mtb and HIV co-infection on cytokine responses." (PMID 39606489, 2024). "Along these lines, our data from the co-infection experiments using S. aureus and H1N1 showed that in the presence of bacteria, at least some pro-inflammatory cytokines (i.e., IL-1β, IL-6, and TNF-α) and type II interferon IFN-γ are elevated on the protein level by H1N1 in M2-MDMs by tendency." (PMID 38261967, 2024). "Additionally, co-infection of pigs with NADC30-like PRRSV-2 strain SDlz1601 and S. suis upregulated IL-1β, IL-6, IL-8, TNF-α, CCL4, IL-10, and INF-β in PAMs." (PMID 38547254, 2024). "High frequencies of PRRSV-2-specific CD8β+ T cells expressing TNF were observed in PRRSV-2 single-infected and PRRSV-2/H3N2 co-infection groups (64.50% vs. 45.05%, respectively), followed by double TNF/IL-2 (6.39% vs. 29.05%, respectively) and TNF/IFN-γ (28.96% vs. 25.63%, respectively) producers." (PMID 37287962, 2023). "A significant difference was revealed in the levels of TNF-α, IL-12, and IL-10 among the patient groups without infection, with latent infection/co-infection, active single, double and triple co-infection." (PMID 36653846, 2023).